BRAF (B-Raf proto-oncogene, serine/threonine kinase)
Diseases named in the same sentence as BRAF in open-access papers (continued):
Sharing a sentence is not in itself a finding about the gene and the disease.
colorectal cancer (continued). "The BRAF V600E mutation in colorectal cancer is detected in approximately 8-12% of patients and the prognosis is extremely poor." (PMID 39310595, 2024). "Further investigations are needed to establish the specific timing of hepatic injury and accumulated cases because this approach is expected to be used more frequently as a second-line treatment for BRAF mutation-positive colorectal cancer." (PMID 39310595, 2024). "The combination of binimetinib (BINI), encorafenib (ENCO), and cetuximab (CET) (“triplet regimen”) was approved in November 2020 in Japan as a second-line treatment for BRAF V600E mutation-positive colorectal cancer." (PMID 39310595, 2024). "Currently, for first-line treatment of advanced colorectal cancer with BRAF V600E mutation, both domestic and international guidelines recommend chemotherapy in combination with bevacizumab as the standard treatment." (PMID 39529955, 2024). "BRAF mutations were common in CDX2-suppressed colorectal cancers (46.2%), but rare in non-CDX2-suppressed cancers (2.2%, Fisher’s exact test p < 0.0001)." (PMID 39452477, 2024). "Given their clinical relevance, the identification and understanding of KRAS and BRAF mutations have become crucial components of personalized medicine approaches in colorectal cancer." (PMID 39006576, 2024). "Genetic mutations are highly important in tumor progression, and mutations in KRAS and BRAF genes are key drivers in colorectal cancer." (PMID 39385899, 2024). "SSL and SSLD lead to microsatellite instability- (MSI-) high colorectal cancer via a serrated pathway characterized by BRAF mutation and CpG island methylation phenotype, and serrated lesions except HP are considered precursors of colorectal cancer." (PMID 38882393, 2024). "The majority of BRAF mutations were identified in right-sided tumors, which aligns with findings from the literature on sporadic colorectal cancer cases." (PMID 39768914, 2024). "An open-label, randomized, phase 2 study aimed to evaluate the efficacy of cetuximab + irinotecan ± vemurafenib in treating BRAF-V600E-mutated colorectal cancer." (PMID 39529955, 2024). "EGFR and PI3K pathway signaling has also been implicated in the adaptive resistance of KRAS-mutant and BRAF-mutant colorectal cancer (CRC) to RAS–MAPK (mitogen-activated protein kinase) pathway intervention." (PMID 38992135, 2024). "Patients with BRAF gene mutations in colorectal cancer have a poor prognosis and a low response to chemotherapy and targeted therapy." (PMID 39555098, 2024). "Mutations in the gene encoding KRAS and BRAF are prevalent in tumors of patients with colorectal cancer." (PMID 38277448, 2024). "Lastly, cluster 5 concentrated on assessing the predictive value of KRAS and BRAF mutations within microsatellite-instability or microsatellite-stability subgroups in the context of colorectal cancer." (PMID 38706597, 2024). "This is the first study showing that the BRAF activating V600E mutation mediates response to BOLD-100 treatment in colorectal cancer." (PMID 39083088, 2024). "Here, we present the case of a patient with BRAF V600E mutation-positive colorectal cancer, who was treated with encorafenib, binimetinib, and cetuximab, and developed grade 3 pancreatitis at our hospital." (PMID 38741697, 2024). "BRAF-mutant microsatellite-stable colorectal cancer (CRC), metastasized to distant sites, is associated with a poor prognosis." (PMID 38962037, 2024). "Although loss of function mutations in RNF43 are currently not directly targetable, they have been associated with the response to anti-EGFR/BRAF combination therapies in microsatellite-stable BRAF-mutated colorectal cancers." (PMID 39452477, 2024). "In BRAF-mutated colorectal cancer, nuclear PD-L1 accelerated tumor progression by interacting with THRAP3." (PMID 38333620, 2024). "The BRAF V600E mutation is found in approximately 10% of colorectal cancers and is associated with a poorer prognosis." (PMID 38888919, 2024).
colorectal cancer (continued). "KRAS and BRAF mutations are important biomarkers in the management of colorectal cancer as they are not only predictive of response to anti-EGFR therapy but are also of prognostic value." (PMID 39364024, 2024). "Downstream of EGFR and KRAS, the protein kinase encoded by the V-Raf murine sarcoma viral oncogene homolog B1 (BRAF) gene is affected by mutations detected in 5–15% of colorectal cancer patients." (PMID 39722096, 2024). "The most studied pathogenic variant BRAF V600E is found in all cases of hairy cell leukemia, up to 60% of skin melanomas and thyroid papillary carcinomas, and up to 10% of colorectal cancers." (PMID 39018206, 2024). "The pooled data suggest that while KRAS and BRAF mutations typically predict poorer outcomes in MSS colorectal cancer, their impact is less pronounced in MSI contexts, with implications varying across different stages of cancer and treatment responses." (PMID 38786299, 2024). "BRAF mutation-positive colorectal cancer is considered to be associated with the mitogen-activated protein kinase (MAPK) pathway for cancer growth." (PMID 39310595, 2024). "Among gastrointestinal (GI) malignancies, BRAF mutations have been extensively studied in colorectal cancer (CRC), detected in about 8–12% of patients with metastatic disease." (PMID 38791902, 2024). "A total of 220 patients with BRAF V600E-mutated colorectal cancer diagnosed at the Cancer Hospital of the Chinese Academy of Medical Sciences from 2014 to 2021 were included." (PMID 39464719, 2024). "Survival analyses of 1112 BRAF‐wild‐type colorectal cancer patients according to the KRAS mutation status." (PMID 39039804, 2024). "In this context, there are limited real-world data on BRAF-mutant colorectal cancer, as it is considered a low-prevalence mutation in colorectal cancer." (PMID 39766040, 2024). "This is supported by a previous article suggesting that KRAS and BRAF mutations with consequent activation of MEK1/2-ERK1/2 signaling increase the risk of lung metastasis in colorectal cancer patients." (PMID 38247543, 2024). "BRAF mutation is a driver mutation in colorectal cancer (CRC), and BRAFV600E mutation is found in 10–15 % of all CRCs." (PMID 38188365, 2024). "Supporting this, analysis from the cancer genome atlas dataset revealed that KRAS mutations were present in 45.5% of right-sided and 40.3% of left-sided colorectal cancers, while BRAF mutations occurred in 24.2% and 2.1% of cases, respectively." (PMID 39628993, 2024). "This is highlighted by the drug combination of dabrafenib plus trametinib, which is indicated in unresectable or metastatic solid tumors with a BRAFV600E mutation, except in colorectal cancer, due to intrinsic resistance to BRAF inhibition." (PMID 39518080, 2024). "If first-line treatment fails, the overall treatment strategy for second-line therapy in colorectal cancer patients with BRAF V600E mutation is primarily based on targeted drugs." (PMID 39529955, 2024). "Previous studies have shown that acquired resistance to BRAF-directed therapy in BRAF V600E colorectal cancer patients is often caused by genomic alterations (e.g., RAS mutations) that lead to reactivation of MAPK signaling." (PMID 38962037, 2024). "We examined the prognostic role of KRAS mutation within 1122 BRAF‐wild‐type colorectal carcinoma cases." (PMID 39039804, 2024). "The method's demonstrated sensitivity and specificity on limited tissue samples suggest its practicality and effectiveness in detecting BRAF mutations, particularly in colorectal carcinoma cases." (PMID 39156294, 2024). "The objective of this study was therefore to determine the frequency of KRAS and BRAF mutations in colorectal carcinomas in our institution." (PMID 39364024, 2024). "The V600E mutation of BRAF is of great importance in human cancer, mostly described in melanomas, papillary thyroid carcinomas, and colorectal carcinomas." (PMID 39591358, 2024).
colorectal cancer (continued). "Here we show that MSI-H, MLH1 hypermethylation, BRAF mutation or KRAS mutations were independently associated with Fn infection in colorectal cancer." (PMID 37772997, 2023). "The present study aims to provide a synthetic and comprehensive review of deep neural networksmodels for predicting the d-MMR/MSI status and BRAF/KRAS mutational status in colorectal cancer." (PMID 38201408, 2023). "Two prior studies have found that a combination of navitoclax and AZD8055 synergistically kills different tumor cells from SCLC and BRAF/KRAS-mutated colorectal cancer." (PMID 36588105, 2023). "Our cohort was analyzed for two key molecular features of colorectal cancer, mismatch repair deficiency, and BRAF status, which enabled us to study the prognostic significance of immune cells independent of these factors." (PMID 36800011, 2023). "Previous studies showed that the mutations of KRAS and BRAF had positive correlations to lung metastasis of colorectal cancer and papillary thyroid carcinoma, respectively." (PMID 36161776, 2023). "BRAF mutations occur early in serrated colorectal cancers, but their long-term influence on tissue homeostasis is poorly characterized." (PMID 37735514, 2023). "Here, we report the first real-world safety information on the use of encorafenib and binimetinib in patients with BRAF V600E-mutated colorectal cancer that was collected during the EPPV study period." (PMID 36355316, 2023). "All the previously identified BRAF mutations in the colorectal cancer patients were confirmed, and additional three new mutations not identified with direct sequencing were detected." (PMID 36758042, 2023). "Patients with V-Raf murine sarcoma viral oncogene homolog B1 (BRAF) V600E-mutated advanced colorectal cancer (CRC) have a poor prognosis, and treatment options that can improve outcome are still under investigation." (PMID 36849918, 2023). "Mutated BRAF mCRC exhibits distinct biological behavior compared to other molecular subtypes of colorectal cancer." (PMID 37958416, 2023). "The identification of novel therapeutic strategies for Colorectal Cancer (CRC) patients with BRAF mutations is mandatory, since most of the current treatments against this tumor type, including novel compounds, show limited efficacy." (PMID 36975409, 2023). "In this systematic review, we evaluated the role of AI in predicting MSI status, KRAS, and BRAF mutations in colorectal cancer." (PMID 38201408, 2023). "BRAF mutation in colorectal cancer has recently received increasing attention for its prognostic effects and targetable properties." (PMID 36912150, 2023). "The rapid feedback activation through EGFR pathways caused by BRAF inhibition in colorectal cancer was subsequently overcome by the addition of anti-EGFR agents, resulting in significant improvements to OS and ORR." (PMID 37124503, 2023). "In colorectal cancer, BRAF p.V600E has been associated with poor clinical prognosis and chemoresistance, increased microsatellite instability, and a higher mutational load." (PMID 38067388, 2023). "In the recent meta-analysis of 67 studies (32,407 patients) evaluating the clinical and pathological significance of the BRAF V600E mutation in colorectal cancer, the largest study collected less than 2000 cases." (PMID 37240418, 2023). "The results of this study should also be considered to develop a treatment strategy and to clarify the safety profile for advanced BRAF V600E-mutated colorectal cancer." (PMID 36355316, 2023). "Pre-disposition for KRAS and BRAF genetic mutations has been suggested as a possible explanation for the previous findings of increased relative risks of colorectal cancer after BOTs." (PMID 37807065, 2023). "All tumours were also screened for MMR status and BRAF mutation status representing two key molecular features of colorectal cancer." (PMID 37002343, 2023).
colorectal cancer (continued). "Rac1b overexpression is also associated with poor outcome of wide-type KRAS/BRAF colorectal cancer treated with FOLFOX/XELOX chemotherapy." (PMID 37373047, 2023). "Here, MLH1 hypermethylation and BRAF mutations were also significantly associated with Fn-positive colorectal cancer samples even though template DNA for Fn amplification was isolated from FFPE samples." (PMID 37772997, 2023). "In another experimental system of colorectal cancer cells expressing BRAF with V600E mutations, inhibition of the mutant BRAF by small kinase inhibitors upregulated claudin 1, which was suppressed in cells with constitutively active mutant BRAF." (PMID 37998722, 2023). "Recently, it has been demonstrated that VC at pharmacological plasma concentrations, acquired intravenously, can selectively kill KRAS- or BRAF-mutated colorectal cancer cells by targeting GAPDH." (PMID 36787291, 2023). "Mismatch repair deficiency (d-MMR)/microsatellite instability (MSI), KRAS, and BRAF mutational status are crucial for treating advanced colorectal cancer patients." (PMID 38201408, 2023). "BRAF mutations are the oncogenic drivers in colorectal cancer and V600 mutations (Class1), which lead to RAS-independent active monomers, are the most common mutation types." (PMID 36694231, 2023). "Triplet and doublet regimens of encorafenib plus cetuximab with and without binimetinib, respectively, were approved in Japan for unresectable, metastatic, BRAF V600E-mutated colorectal cancer (mCRC) that had progressed after 1–2 prior chemotherapies." (PMID 36355316, 2023). "BRAF is an oncogenic kinase and contains diverse mutations in approximately 10% colorectal cancer (CRC)." (PMID 37853469, 2023). "The BRAFV600E mutation, the most common BRAF genetic alteration, occurs in 66% of cutaneous melanomas and 25% of colorectal cancers." (PMID 38111008, 2023). "Human colorectal cancer cells harboring KRAS or BRAF mutations were selectively killed in vitro when exposed to high levels of vitamin C." (PMID 37107291, 2023). "The BRAF V600E mutation accounts for approximately 10% of all colorectal cancer, 2% of non-small cell lung cancer, 15.7% of all breast cancers, 50% of cutaneous melanoma and thyroid cancer, 6% of brain cancers, and 100% of hairy cell leukemia." (PMID 38136350, 2023). "KRAS/BRAF mutations (mutKRAS/mutBRAF) are unfavorable prognostic factors for colorectal cancer (CRC) metastases to the liver and lungs." (PMID 37886242, 2023). "Currently, another prospective post-marketing surveillance study is ongoing in Japan as a pharmacovigilance activity of the triplet and double regimens for BRAF V600E-mutated colorectal cancer patients to assess the safety and efficacy of each regimen." (PMID 36355316, 2023). "BRAF mutations are found with a high frequency (up to 45%) in MSI colorectal cancer, with mostly exclusive prevalence of p.V600E." (PMID 37190216, 2023). "BRAF variant status is frequently assessed in colorectal cancer given its prognostic and treatment implications in the MMR proficient (MMRp) colorectal cancer." (PMID 38344144, 2023). "For example, in the analysis of KRAS, NRAS, and BRAF mutations in 850 colorectal cancer (CRC) cases, the concordance rate was 88.6%, accounting for all mutations including those not in the Idylla cartridge by design." (PMID 37174112, 2023). "Previously, we newly identified, BRAF L525R-mutation, in the activation segment of the kinase in colorectal cancer patient." (PMID 36856908, 2023). "BRAF V600E mutation, which changes codon 600 from valine to glutamate, accounts for about 95% of BRAF mutant colorectal cancers." (PMID 37302081, 2023). "We conducted an early post-marketing phase vigilance (EPPV) study to collect reports of adverse drug reactions (ADRs) during the first 6 months after the approval of the triplet and doublet regimens for BRAF V600E-mutated colorectal cancer." (PMID 36355316, 2023).
colorectal cancer (continued). "On the contrary, our group found that nuclear HES1 expression is lost in 91% of sessile serrated adenomas/polyps (SSA/p) and most of the right-sided colorectal cancer which commonly harbors BRAF or KRAS mutation." (PMID 37749297, 2023). "KRAS and BRAF mutation rates in colorectal cancer (CRC) reported from various mono-ethnic studies vary amongst different ethnic groups." (PMID 38139338, 2023). "Somatic BRAF p.V600E variants are exceedingly rare in LS colorectal cancer, but are present in approximately half of sporadic mismatch repair deficient (MMRd) colorectal cancers." (PMID 38344144, 2023). "In the case of CIMP-high colorectal cancer, spontaneous aging-like promoter hypermethylation makes organoids more sensitive to transformation by BRAF V600E mutation, which leads to CIMP." (PMID 37234978, 2023). "The RAS/BRAF mutation is very common in colorectal cancer and plays an important role in tumorigenesis and progression." (PMID 36672503, 2023). "This combined treatment shows potential in overcoming cetuximab resistance in colorectal cancer (CRC) cells that carry KRAF/BRAF mutations or have developed acquired resistance." (PMID 37558749, 2023). "According to a recent study, VC can selectively kill KRAS/BRAF-mutated colorectal cancer cells by targeting GAPDH." (PMID 36787291, 2023). "The BRAF mutations were tested in only 110 (45.5%) of the colorectal cancer patients, and 11 (4.9%) were V600E mutants." (PMID 36672302, 2023). "BRAF mutant colorectal cancer, a low prevalent mutation, has rapid progression, poor prognosis, and low response rates to standard therapy." (PMID 37302081, 2023). "The combined therapy with EGFR, BRAF, and MEK inhibition has shown efficacy in BRAF-mutated colorectal cancer, demonstrating the clinical value of using ERBB inhibition to enhance targeting of an MAPK oncogene." (PMID 36752207, 2023). "More than half of the eye disorders developed within 1 week after the administration started, which was similar to the findings in an expanded access program of the triplet regimen for advanced BRAF V600E-mutated colorectal cancer in Japan." (PMID 36355316, 2023). "Despite being in the same pathway, mutations of KRAS and BRAF in colorectal carcinomas (CRCs) determine distinct progression courses." (PMID 37870961, 2023). "Encorafenib is another BRAF inhibitor, currently approved in combination with the MEK-inhibitor binimetinib for BRAF-mutated metastatic melanoma and colorectal carcinoma." (PMID 37435488, 2023). "There is evidence that BRAF mutations confer uncontrolled growth and proliferation among colorectal carcinoma cells." (PMID 38136294, 2023). "For colorectal cancer, the author overserved co-occurrence of oncogenic BRAF mutations with mutations in the ubiquitin ligase RNF43." (PMID 36275468, 2022). "In conclusion, our study confirms the established association between diabetes and colorectal cancer risk, and suggests that it particularly increases the risk of BRAF‐mutated tumors." (PMID 35383926, 2022). "For example, this model is a microsatellite unstable (MSI) colorectal cancer model harbouring a BRAF V600E mutation and, as expected, knockout of BRAF led to a strong loss of viability in both 80% and 5% conditions (top 10% dependencies)." (PMID 35368031, 2022). "Recurrent molecular characteristics of the colorectal cancer cell lines panel that confer sensitivity to specific BRAF inhibitors include, as expected, BRAF mutations conferring sensitivity to 4 of the 5 inhibitors." (PMID 36295658, 2022). "Recently, the combination of the BRAF inhibitor Encorafenib with the EGF-R inhibitor Cetuximab has been reported as the new standard for the treatment of metastatic BRAF-mutated colorectal cancer." (PMID 35454846, 2022). "BRAF mutations, found in 8% to 12% of colorectal cancers, are generally associated with a poor prognosis and are more common in proximal tumors." (PMID 35383926, 2022).